IL1B (interleukin 1 beta)
Diseases named in the same sentence as IL1B in open-access papers (continued):
Sharing a sentence is not in itself a finding about the gene and the disease.
febrile seizures (4 papers, 2011 to 2024). "Another clinical study demonstrated that febrile convulsions increase the levels of cytokines IL-1β, IL-6, and TNF-α in cerebrospinal fluid." (PMID 39315097, 2024). "In febrile seizure patients, serum IL-1β levels were at a 4-fold increase and HMGB1 levels were at a 1.3-fold increase higher than the fever only controls (both p < 0.05)." (PMID 21989210, 2011). "IL-1β serum levels were significantly higher in our febrile seizures patients than in febrile children without seizures." (PMID 21989210, 2011).
Fulminant hepatitis (4 papers, 2015 to 2022). Acute hepatitis complicated by acute liver failure with hepatic encephalopathy occurring less than 8 weeks after the onset of jaundice. "NLRP3 is a component of the inflammasome pathway that regulates maturation of the inflammatory cytokines interleukin (IL)-1b and IL-18, and in the absence of REV-ERBα, dysregulated expression of Nlrp3 leads to increased IL-1b and IL-18 and susceptibility to fulminant hepatitis." (PMID 39872076, 2022).
generalized pustular psoriasis (4 papers, 2020 to 2023). A rare and extreme form of psoriasis characterized by the appearance of sterile pustules which can take many patterns. "For example, canakinumab, an anti-IL-1β monoclonal antibody, has been used to treat a generalized pustular psoriasis patient and resulted in complete remission of the lesions." (PMID 32528469, 2020).
geographic atrophy (4 papers, 2015 to 2022). "In macular RPE tissue from donors with geographic atrophy that is associated with late AMD, an increase of NLRP3, ASC, Caspase-1, IL-1β, and IL-18 proteins was observed." (PMID 35805159, 2022). "In another study, no significant increase in IL-1β gene expression was found in the RPE of patients with geographic atrophy (GA), and a non-significant increase in IL-1β levels in the aqueous humor of dry AMD patients compared to healthy controls." (PMID 31379825, 2019). "Interestingly, it was found that there are increased level of NLRP3 protein, IL-1β and IL-18 mRNA in the RPE of donor eyes from individuals with geographic atrophy and neovascular AMD." (PMID 26504591, 2015). "Other reports investigating the role of inflammasome in the pathogenesis of AMD observed an increased content of NLRP3, ASC, Caspase-1, IL-1β, and IL-18 protein in RPE tissue from the macula region of donors with geographic atrophy (GA) compared to non-diseased controls." (PMID 35805159, 2022).
glomerular diseases (4 papers, 2020 to 2025). "NLRP3 inflammasome was activated in tubulointerstitial and glomerular diseases, promoting proinflammatory cytokines IL-1β and IL-18 production and excretion, causing renal inflammatory injuries." (PMID 32116724, 2020).
gynecological cancers (4 papers, 2014 to 2023). "The immunoproteomic profiles also demonstrated that BVAB associated with gynecologic cancers share a core pro-inflammatory response mediated through upregulated expression of IL-1β." (PMID 35869172, 2022). "Vaginal Lactobacillus may protect from gynecological cancers by inhibiting pro-inflammatory bacteria, such as those implicated in pelvic inflammatory disease, and by reducing inflammatory cytokines IL-1β and IL-6." (PMID 34178459, 2021).
herpes infections (4 papers, 2015 to 2024). "Additionally, there can be non-inflammasome sources of IL-1β and IL-18, making it challenging to consistently draw direct links between inflammasome activation and pathological observations associated with IL-18 and IL-1β in herpes infections." (PMID 35038917, 2022). "NLRP3 inflammasome has also been the most reported in herpes infections, with consequent Caspase-1 and IL-1β activation." (PMID 31367214, 2019). "In summary, our studies demonstrate that the post-genome recognition event of IFI16’s acetylation by histone acetyltransferase p300 is required for the IFI16-mediated innate immune responses of inflammasome induction, IL-1β and interferon-β production during herpesvirus infections." (PMID 26134128, 2015). "One possible mechanism involves the uncontrolled release of proinflammatory cytokines (e.g., IL-1β and TNF-α) in response to herpesvirus infection, supporting the proliferation of periodontopathogens and resulting in tissue destruction." (PMID 38251365, 2024).
immunotoxicity (4 papers, 2014 to 2025). "Acute cytotoxicity was tested by measuring release of lactate dehydrogenase (LDH) and immunotoxicity was determined by measuring secretion of pro-inflammatory cytokines interleukin-1-beta (IL-1β) and tumor necrosis factor-alpha (TNF-α)." (PMID 25473947, 2014). "Significant increases in immune-related protein indicators (NF-κB, TNF-α, IL-1β and TLR4) were detected in our study, indicating that 6:2 FTSA amplifies the inflammatory damage profile and induces organismal immunotoxicity in zebrafish larvae." (PMID 37235273, 2023). "Similarly, Wang and colleagues reported that T-2 induced the overexpression of proinflammatory genes and upregulated the mRNA expression of TNFα, IL-1β, and IL-6, leading to the activation of the JAK-STAT signaling pathway contributing to immunotoxicity." (PMID 40864073, 2025).
intracranial hypertension (4 papers, 2020 to 2025). A finding characterized by increased cerebrospinal fluid pressure within the skull. "Another group of experiments on animal models of intracranial hypertension showed that increased ICP was significantly associated with increased levels of cytokines, such as IL-6, IL-18, IL-1α and IL-1β." (PMID 36441671, 2022). "Animal experiments reflect these interlinks at the molecular level, as intracranial hypertension augments the inflammatory response in ARDS, characterized by increased levels of TNFα, IL-6 and IL-1β, and microglial activation." (PMID 33163005, 2020).
invasive ductal carcinoma (4 papers, 2015 to 2019). "IHC analysis of ductal adenocarcinoma cases (n = 20) demonstrated that IL-1β expression was significantly increased in TNBC compared to HR+ tumors." (PMID 26327350, 2015). "Like IRIS, the expression of IL-1β is steadily increase from very low in normal breast epithelium, to relatively high in patients with ductal carcinoma in situ (DCIS), to even higher in patients with invasive ductal carcinoma (IDC) with no relapse, and is highest in patients with IDC with relapse." (PMID 29262555, 2017).
Jaundice (4 papers, 2014 to 2022). Yellow pigmentation of the skin due to bilirubin, which in turn is the result of increased bilirubin concentration in the bloodstream. "This is not without precedent, since GUDCA was demonstrated to inhibit the production of TNF-α and IL-1β in astroglial cells by preventing the maturation of these cytokines and their consequent release in an experimental model of jaundice, thus preventing astroglial reactivity." (PMID 31024256, 2019). "Finally, for the discrimination of PDAC in the presence of jaundice from benign controls with jaundice, a panel of IP-10, IL-8, IL-1b and PDGF demonstrated improvement over CA19-9 in the training (AUC 0.810 vs. 0.614) and test set (AUC 0.857 vs. 0.659)." (PMID 24884871, 2014).
Klebsiella Infections (4 papers, 2012 to 2023). Infections with bacteria of the genus KLEBSIELLA. "Likewise IFNγ-deficient mice, IL1R−/− mice are exquisitely susceptible to Klebsiella infection demonstrating the importance of IL1β-controlled responses for host survival and bacterial clearance." (PMID 30452654, 2019). "In vitro experiments confirmed the contribution of NLRP3 to caspase-1 activation and IL1β release following Klebsiella infection." (PMID 30452654, 2019). "Although lung-resident innate-like T cells did not constitutively express IL-17A as assessed by the hNGFR reporter, γδ T cells, iNKT cells and other CD3ε+ cells expressed hNGFR within 24 hr after Klebsiella infection or 8 hr after administration of IL-1β and/or IL-23." (PMID 22768117, 2012). "Several pro-inflammatory cytokines including IL-6, IL-1β, and TNF-α were also decreased after astragaloside IV treatment, indicating that astragaloside IV could inhibit inflammation-related apoptosis caused by Klebsiella infection by inhibiting TGF-β1 signaling pathway." (PMID 37493767, 2023).
laryngeal carcinoma (4 papers, 2020 to 2025). Carcinoma that arises from the laryngeal epithelium. "First, the sample size of laryngeal carcinoma and parotid gland cancer was relatively small, therefore the correlation between IL-1B/ IL-1RN SNPs and the risk of laryngeal carcinoma and parotid gland cancer was not analyzed." (PMID 33472637, 2021). "Higher level of IL-1β in peripheral blood mononuclear cell (PBMC) cultures isolated from venous blood in the patients with laryngeal carcinoma is associated with lower 3-year and 5-year survival." (PMID 32577124, 2020). "Western blot was performed to test the expression of IFI16, caspase-1 and IL-1β protein in 3 pairs of primary laryngeal carcinoma and their normal para-laryngeal tissues collected from 3 patients with laryngeal cancer after surgery." (PMID 32577124, 2020). "The significantly increased expression of IFI16 (2.32 ± 0.12-fold), caspase-1 (1.85 ± 0.13-fold), and IL-1β protein (1.93 ± 0.10-fold) was detected in laryngeal cancer tissues compared with that in adjacent tissues." (PMID 32577124, 2020). "For laryngeal cancer, we found CXCL1 (sensitivity = 81.48, specificity = 79.17, ROC Area = 0.8596, threshold = 0.1423) as a strong candidate and IL1b (sensitivity = 75.86, specificity = 72, ROC Area = 0.7462, threshold = 0.1681) as weak candidate biomarker." (PMID 38175424, 2024).
lipodystrophy (4 papers, 2014 to 2024). A congenital or acquired disorder characterized by abnormal loss or redistribution of the adipose tissue in the body. "Furthermore, AT inhibited lipodystrophy-associated increase of plaque macrophage infiltration and aortic expression of proinflammatory cytokines (Mcp-1, Il-1β, and Il-6) in Seipin/Apoe dKO mice, as shown by CD68 immunohistochemical staining and real-time quantitative PCR analysis, respectively." (PMID 38525541, 2024). "Though, in order to deepen our studies on the inflammatory profile of lipodystrophy we analyzed the plasma levels of cytokines involved in the development of IR such as IL-1β, IL-6 e TNF-α." (PMID 29449893, 2018). "Importantly, IL-6, and to a lesser extent IL-1β, have been linked to HIV lipodystrophy." (PMID 34383714, 2021).
lymphedema (4 papers, 2009 to 2025). Excess fluid collection in tissues, causing swelling. "To determine the association of inflammatory cytokines with filarial lymphedema, we measured the plasma levels of IL-1β, IL-6, IL-12, and TNF-α in the four groups of subjects." (PMID 22685406, 2012). "Inflammation plays a pivotal role in the pathophysiology of lymphedema, with IL-1β being a key mediator of chronic inflammation and fibrosis." (PMID 40244338, 2025). "To address the role of Th17 cells in filarial lymphedema, we examined the expression of IL-17A, IL-17F, IL-21 and IL-22 as well as the upstream inducing cytokines IL-23, IL-6 and IL-1β in PBMCs of lymphedema patients following BmA or PPD stimulation." (PMID 19381284, 2009). "IL-1β is a critical mediator in inflammation and tissue damage in lymphedema." (PMID 40244338, 2025). "The observed reduction in IL-1β levels suggests that CBD-THC hydrogel formulations could serve as an alternative or complementary approach to corticosteroids for managing inflammation in lymphedema." (PMID 40244338, 2025).
macular degeneration (4 papers, 2019 to 2025). Loss of vision in the central portion of the retina (macula), secondary to retinal degeneration. "Our findings show that the levels of NLRP6, IL-1β and IL-18 in the peripheral blood of patients with macular degeneration are increased." (PMID 40837366, 2025). "In the future, cell experiments and other methods should be used to clarify the precise regulatory pathways involving NLRP6, IL-1β and IL-18 in macular degeneration." (PMID 40837366, 2025). "At the same time, the AUC values of IL-1β and IL-18 were determined to be 0.8089 and 0.7838 by ROC curve analysis, indicating their utility as peripheral blood biomarkers in diagnosing macular degeneration." (PMID 40837366, 2025). "In macular degenerative diseases, IL-1β inhibits glutamate transport, leading to excessive accumulation of glutamate in the retina and inducing degeneration of rod cells." (PMID 39567494, 2024). "High levels of IL-1β are detected in the eyes of AMD patients and the same applies to models of macular degeneration wherein IL-1β is generated by microglia/macrophages." (PMID 33246504, 2020). "In addition, the levels of proinflammatory cytokines such as IL-1β and TNF-α were increased in patients with macular degeneration, indicating chronic inflammatory diseases." (PMID 40837366, 2025).
Majeed syndrome (4 papers, 2017 to 2023). Majeed syndrome is a rare genetic multisystemic disorder characterized by the triad of chronic recurrent multifocal osteomyelitis, congenital dyserythropoietic anemia, and variable transient inflammatory dermatosis. "Recently, lipin-2 has been reported to regulate P2X7 receptor sensitization to limit overactivation of NLRP3 inflammasome, which may provide clues to better understand the molecular features that characterize the high IL-1β production found in Majeed syndrome patients with LPIN2 mutations." (PMID 29255148, 2017). "Therapeutically blocking the IL-1RI or IL-1β has been utilized in 10 patients with Majeed syndrome and all have reported significant benefit with resolution of the inflammatory bone disease and normalization of inflammatory markers." (PMID 33670882, 2021). "However, certain syndromic forms of CNO, like Majeed syndrome and deficiency of the IL-1 receptor antagonist (DIRA), have been linked to specific gene mutations (LPIN2 and IL1RN), shedding light on the role of IL-1β in inflammation." (PMID 38137947, 2023).
malignant glioma (4 papers, 2006 to 2021). A grade III or grade IV glioma arising from the central nervous system. "For instance, overexpression of IL-1β in human malignant gliomas was associated with cancer cell proliferation, migration and invasion 40,41." (PMID 33995625, 2021). "In addition, IL-1β, IL-6 and IL-8 and their cognate receptors are also elevated in malignant gliomas." (PMID 22330721, 2012).
MALT lymphoma (4 papers, 2015 to 2022). An indolent, extranodal type of non-Hodgkin lymphoma composed of small B-lymphocytes (centrocyte-like cells). "In the comparison by subtype or GI lesions, serum interleukin (IL)-8 (P = 6.7E−05), IL-4 (P = 7.5E−05), and IL-1β (P = 0.0043) levels showed significant differences among subtypes, being particularly elevated in follicular lymphomas (FL) and mucosa-associated lymphoid tissue (MALT) lymphomas." (PMID 26674732, 2015). "In summary, analysis of Th1/Th2 cytokine levels in serum samples shows that IL-8 levels were elevated in GI FL and MALT lymphomas, whereas IL-4 and IL-1β levels were elevated in MALT lymphomas." (PMID 26674732, 2015). "Serum IL-4 and IL-1β levels were elevated in MALT lymphoma cases compared with healthy controls (P = 0.00019 and 0.024, respectively)." (PMID 26674732, 2015). "Furthermore, IL-1β and IL-23 levels were also higher in the MALT lymphoma compared to the paired normal tissues." (PMID 32063899, 2019). "In the present study, elevation of IL-4, IL-1β, and IL-8 levels was detected in MALT lymphomas." (PMID 26674732, 2015).
metastasis (4 papers, 2014 to 2023). The spread or migration of cancer cells from one part of the body (where they first appeared) to another. "One of these, IL1B, has been shown to increase CCL2 in follicular thyroid carcinoma, leading to lymph node metastasis." (PMID 25277206, 2014).
multiple system atrophy (4 papers, 2017 to 2024). Multiple system atrophy (MSA) is a neurodegenerative disorder characterized by autonomic failure (cardiovascular and/or urinary), parkinsonism, cerebellar impairment and corticospinal signs with a median survival of 6-9 years. "IL-1β and IL-8 had positive correlations with Unified Multiple System Atrophy Rating Scale part 1 and 2, respectively, in MSA-C." (PMID 28438224, 2017). "Furthermore, pro-inflammatory cytokine levels, such as IL-1β in the CSF, can distinguish between PD and multiple system atrophy as well as progressive supranuclear palsy." (PMID 37375830, 2023). "Other works revealed increased levels of interferon γ, IL-10, IL-18, IL-1β, IL-4, IL-6, transforming growth factor β1, and Tumor Necrosis Factor-α in PSP and Multiple System Atrophy when compared to PD." (PMID 39176092, 2024).
Mycoplasma pneumonia (4 papers, 2022 to 2025). "Moreover, ATF3 can inhibit the release of inflammatory factors TNF‐α, IL‐1β, IL‐6, and IL‐18 induced by Mycoplasma pneumonia." (PMID 37385291, 2025). "One in vitro study of MGD on serum of children with Mycoplasma pneumonia also showed that MGD suppressed L-1β, IL-18, TNF-α, down-regulated NLRP3, pro-IL-1β, Caspase-1, pro-Caspase-1, and GSDMD-N in infected cultures and mitigated NLRP3 overexpression-induced pyroptosis." (PMID 36120338, 2022). "The cytokines tumor necrosis factor-alpha, interleukin-8, interleukin-6, and interleukin-1 beta were detected in the airway secretions of children infected with RSV and Mycoplasma pneumonia, which may act as a double whammy of respiratory pathogens and correlate with severe pathogenesis." (PMID 36422931, 2022).
myelodysplastic syndrome (4 papers, 2021 to 2025). A clonal hematopoietic disorder characterized by dysplasia and ineffective hematopoiesis in one or more of the hematopoietic cell lines. "This study investigated the expression levels of NLRP6, IL-1β and IL-18 in patients with myelodysplastic syndrome (MD) and their potential diagnostic value." (PMID 40837366, 2025).
myeloproliferative neoplasm (4 papers, 2022 to 2025). A clonal hematopoietic stem cell disorder, characterized by proliferation in the bone marrow of one or more of the myeloid (i.e., granulocytic, erythroid, megakaryocytic, and mast cell) lineages. "Increased activity of IL-1β has been implicated in various pathological conditions including myeloproliferative neoplasms (MPNs)." (PMID 36100613, 2022).
neonatal encephalopathy (4 papers, 2013 to 2020). "Rapid increases in the levels of the main inflammatory cytokines TNF-α, IL-1β, and IL-6 under oxidative stress cause direct injury to the ischemic site and positively correlate with the severity of neonatal encephalopathy." (PMID 32074976, 2020). "In a rodent model of neonatal encephalopathy, neurons are the first cells to produce excessive levels of IL-1β, earlier than microglia and astrocytes." (PMID 30621715, 2019).
ovarian endometriosis (4 papers, 2014 to 2024). A non-neoplastic disorder characterized by the growth of endometrial tissue in the ovaries. "Increased expression of NLRP3 inflammasome and activation of IL-1β has been associated with the progression of ovarian endometriosis, and inhibitor NLRP3 using MCC950 prevents ovarian endometriosis." (PMID 39769450, 2024). "For instance, endometrioma, a form of endometriosis in the ovary, is a highly inflammatory condition which would expectedly result in high levels of urinary IL-1β." (PMID 25403235, 2014). "Similarly, MCC950 (an NLRP3 inhibitor) prevents ovarian endometriosis and the expression of NLRP3 and IL-1β in the endometrial stromal cells and cyst-derived stromal cells." (PMID 39769450, 2024).